BRAF (B-Raf proto-oncogene, serine/threonine kinase)
Diseases named in the same sentence as BRAF in open-access papers (continued):
Sharing a sentence is not in itself a finding about the gene and the disease.
tumor (continued). "Our study supports the prognostic impact of T cell score independent of age, gender, stage, grade, MSI, BRAF status, tumor location, and the B cell score." (PMID 36800011, 2023). "Indeed, the effects of tumor suppressor inactivation on growth across oncogenic KRAS-, BRAF-, and EGFR-driven tumors were uncorrelated (Spearman ρ = 0.41 for BRAF versus G12C, ρ = 0.14 for EGFR versus G12C)." (PMID 37828026, 2023). "It has been reported that oncogenic activation of KRAS/BRAF/MEK signaling stimulates Wnt/β-catenin pathway by β-catenin/TCF4 complex activation via Frizzled co-receptor LRP6 phosphorylation, which in turn promotes tumor growth and invasion." (PMID 37483610, 2023). "In our analysis, we found 18 fungal species overabundant in tumor tissue with no BRAF V600E present, including Phaeoacremonium minimum UCRPA7 and Saccharomyces cerevisiae YJM1615." (PMID 36834564, 2023). "In the primary tumor, BRAF V600E was present with a tumor frequency of 12%, whereas in the recurrent tumor, it was <1%, despite the fact that the patient had not been treated with BRAF targeted agent." (PMID 37373295, 2023). "In contrast, BRAF-negative tumours had a tendency for false positive AI predictions with increasing sample size (p > 0.3)." (PMID 37570213, 2023). "The combination of a dual BRAF and MEK inhibitor with anti-PD-1 mAb could lead to more tumor infiltration of immune cells and better anti-tumor efficacy in a CD8+ T cell-dependent way." (PMID 37631380, 2023). "Furthermore, the impact of different tumor suppressors on tumor number varied across oncogenic KRAS, BRAF, and EGFR contexts." (PMID 37828026, 2023). "The rationale behind treating xenografted tumor models with pitavastatin alone without BRAF inhibitor was that the sensitivity to statin was not BRAF inhibitor dependent." (PMID 37277330, 2023). "In contrast, if the TMB value is low, such patients might be more likely to benefit from adjuvant BRAF and MEK inhibitors, assuming that their tumor tissue is less heterogeneous." (PMID 35192052, 2023). "In another analysis of a subgroup of patients with unresectable mCRC based on BRAF status, high tumor infiltration CD68+ macrophages had no prognostic role in BRAF mutant mCRC (data not shown)." (PMID 37302081, 2023). "By performing parallel studies with matched patient-derived organoids generated from the same patients, we confirmed that induction of immune genes by BRAF/MAPK inhibition is tumor cell intrinsic and does not depend on cells in the tumor microenvironment." (PMID 36702949, 2023). "Common genes used for CRC DNA mutation detection include BRAF and KRAS, but these tumor markers are not sensitive or specific enough to show CRC." (PMID 36968824, 2023). "In parallel, a randomized non-inferiority trial involving RAS/BRAF status and primary tumor sites to evaluate the addition of anlotinib vs. bevacizumab to XELOX/FOLFOX is also required in the future." (PMID 37727206, 2023). "With this retrospective study we also assessed the potential correlation between the recently found but not yet implemented marker TSR and molecular tumour markers BRAF, KRAS and MSI." (PMID 37344790, 2023). "Furthermore, AK2 is an AMP-sensing negative regulator of BRAF (B-Raf proto-oncogene) in tumorigenesis, and monitors cellular AMP levels linking metabolic status to the tumor." (PMID 36982634, 2023). "We showed that supplementing the current standard-of-care combination of the BRAF inhibitor encorafenib plus an anti-EGFR antibody (panitumumab) with the FDA-approved COX2 inhibitor celecoxib significantly and consistently improved tumor growth inhibition." (PMID 36759733, 2023). "The occurrence of BRAF p.V600E in non-pilocytic pLGGs varies significantly depending on the tumor’s histology and location." (PMID 37397394, 2023). "Mutational status in tumor tissue comprised 14 patients (67%) with KRAS mutations, nine without detection of KRAS, NRAS, or BRAF mutations (wild-type), and four without available mutational testing." (PMID 37903871, 2023).
tumor (continued). "The tumor tissue DNA was analyzed for genomic abnormalities, and the resected specimen indicated that the tumor was MSI-high and negative for RAS/BRAF mutation." (PMID 37386324, 2023). "Nevertheless, there could be a strong rationale for combining anti-BRAF therapy with CDK4/6 inhibition, especially in neo-adjuvant settings, to improve the probability of effective tumor surgical resection." (PMID 37964967, 2023). "BRAF is prototypical of oncogenes that can be targeted therapeutically and the treatment of BRAFV600E melanomas with RAF and MEK inhibitors results in rapid tumor regression." (PMID 36700386, 2023). "IHC also demonstrated “patchy” BRAF V600E positivity, although DNA analysis of the tumor did not demonstrate any BRAF V600E alteration." (PMID 37192626, 2023). "Preclinical and clinical data have suggested that blocking the MAP kinase signaling cascade by BRAF inhibitors such as encorafenib, and MEK inhibitors such as binimetinib, can block not only growth suppression of tumor cells, but can also lead to a disturbance in the retinal pigment epithelium." (PMID 36355316, 2023). "Long-term follow-up confirms the trend of separation between the combination and nivolumab group curves in patients with BRAF-mutant tumours, not seen in patients with BRAF wild-type tumours." (PMID 37404764, 2023). "For tumor (sub)types with a high prevalence of NTRK fusions, including MSI-H/dMMR, BRAF and RAS wildtype mCRC, upfront testing with RNA-NGS, FFPE-TLC, or qRT-PCR could be a reasonable approach." (PMID 37067589, 2023). "This mutation is noticed in 1–3% NSCLC patients with a history of smoking and the altered BRAF gene, forms a non-native BRAF protein that fuels the tumor cell growth." (PMID 37970206, 2023). "Furthermore, tunlametinib combined with BRAF/KRASG12C/SHP2 inhibitors or docetaxel showed synergistically enhanced response and marked tumor inhibition." (PMID 37808191, 2023). "The presence of both BRAF p.V600E and TERT promoter was significantly correlated with patient age, extrathyroidal extension, lymph node metastasis, distant metastasis, disease stage, tumor recurrence and mortality." (PMID 37510219, 2023). "While RAS itself is considered as “undruggable”, inhibitors of both mutant BRAF and wild type MEK have been approved as first line treatments for locally-advanced and metastatic melanoma and have demonstrated improved tumor response rate and progression free survival (PFS)." (PMID 35409020, 2022). "We found a significant delay in primary tumor growth generated by 8505c and CAL62 cells in the DEL-22379-treated groups compared with animals treated with vehicle, but with greater potency in BRAF-mutant cells." (PMID 36056964, 2022). "In short, the activation of BRAF-V600E results in downstream phosphorylation and activation of ERK (extracellular signal-regulated kinase) which, after nuclear translocation, upregulates tumor-promoting genes and downregulates tumor-suppressor genes." (PMID 35406382, 2022). "We sought to understand general practice patterns, the influence of molecular diagnostics (e.g., testing for KRAS, NRAS, BRAF, and MSI), tumor sidedness, and patient-centric factors on treatment selection utilizing in-person surveys and three hypothetical patient case scenarios." (PMID 36005180, 2022). "Although mutant RAS and BRAF status are known to be associated with LTP, these tumor characteristics were not routinely measured over the last decade, resulting in high rates of missing data." (PMID 35585138, 2022). "RAS-mutant, BRAF, and RET/NTRK fusions were mutually exclusive events in every tumor analyzed." (PMID 35015563, 2022). "In addition, the combination of A3 and A4 with BRAF/MEK inhibitors potently inhibited cell growth and tumor relapse in a xenograft model." (PMID 36271429, 2022).
tumor (continued). "At the time of BRAF plus MEK inhibitor initiation, 90% of patients had extracranial metastasis, with a median of 2 extracranial organs involved, and 90% of patients had their primary tumor controlled." (PMID 36579260, 2022). "In comparison to full length protein, the truncated BRAF V600E tends to form homodimer and activates MAPK signaling regardless of RAFi 76, 81, blocking of which can abolish persistent ERK activation and sensitize tumor cells to RAFi." (PMID 35966590, 2022). "Finally, the evaluation of methylation in ctDNA via ddPCR, such as the detection of RASSF1A or paraoxonase 3 (PON3), may suggest the state of the disease and survival outcomes in CM patients, even in the absence of tumor mutation data for BRAF, RAS or EGFR genes." (PMID 35887633, 2022). "Prospectively enrolled patients with previously untreated mCRC undergoing physician discretion SOC tissue genotyping submitted pretreatment blood samples for comprehensive circulating tumor DNA (ctDNA) analysis with Guardant360 and targeted RAS and BRAF analysis with OncoBEAM." (PMID 35525184, 2022). "Moreover, AK2/BRAF interaction was abrogated by RAS activation in in vitro assay and cell model and in a mouse model of HRASG12V-driven HCC, and AK2 ablation promoted tumor growth and BRAF activity." (PMID 35585049, 2022). "Such comparator datasets will also provide information on the impact of novel targeted therapies (BRAF and MEK inhibitors) on similar tumour control, neuroendocrine, and neurobehavioural outcomes in this vulnerable group and require intensive collaborative efforts." (PMID 35159015, 2022). "In order to evaluate the trafficking of immune cells to tumor, we generated spheroids from LND1 cells, a BRAF wt MM cell line, to whom we added each of the three different population of PBMCs, isolated from blood of healthy donors, of a responder (RES) and of a non-responder (NRES)." (PMID 35042524, 2022). "However, individual (e.g., age, sex, partnership) and disease-related (e.g., tumor burden, experience with ICI or BRAF-MEK inhibitors) resulted in variation of the preferences." (PMID 36358844, 2022). "Firstly, some rare tumor types did not have sufficient sample sizes to capture the full BRAF expression and alteration spectrum to establish moderate associations." (PMID 35910024, 2022). "With high expression levels of PDL-1 and EGFR on the cell surface plus both BRAF V600E and KRAS G13D existing within its genome, the A375 KRAS G13D mutant isogenic line is an ideal model suited for future studies focused on the tumor microenvironment and integrated combination therapy strategies." (PMID 36358868, 2022). "We analysed tumour tissue and performed DNA analysis for mutations in KRAS, BRAF and analyses for MSS/MSI in all patients except 8 of 257 (3.1%) where tumour tissue was not obtained." (PMID 34887523, 2022). "We did not have data regarding tumor molecular subtypes in the present study, including microsatellite instability-high (MSI/dMMR) tumors, RAS, and B-Raf (BRAF) gene mutations." (PMID 35100975, 2022). "Two BRAF‐rearranged tumours fell in the “LGG, PA/GG ST” class and no class was assigned with certainty to the two remaining tumours with a BRAF rearrangement." (PMID 35836307, 2022). "Current National Comprehensive Cancer Network guidelines recommend the use of a fluoropyrimidine, with or without bevacizumab, or for patients with RAS/BRAF wild-type tumours and left-sided disease, an anti-EGFR antibody." (PMID 35440667, 2022). "Studies of primary CRC have shown that mismatch repair status is important in their interpretation of BRAF mutations status, and that mutBRAF does not affect OS and DFS in patients with MSI tumours." (PMID 34887523, 2022). "Finally, we evaluated the correlation between ctDNA levels and metabolic tumour burden (MTB) prior to treatment and at the time progression in a subgroup of patients treated with BRAF/MEK inhibitors (N = 15)." (PMID 34373567, 2022).
tumor (continued). "Because of the ongoing possibility of long-term survival with immune checkpoint inhibitors and the palliative effect of BRAF/MEK-inhibitors, high numbers of patients may be receiving anti-tumor treatment near death." (PMID 35247992, 2022). "Therefore, our study suggests that BRAF V600E constitutively activates mitochondrial ERK, thereby inhibiting GSK‐3‐dependent CypD phosphorylation, and thus making BRAF V600E mutant tumour cells more resistant to mPTP pore opening and subsequent cell death." (PMID 35748101, 2022). "The authors attributed the tumor-promoting effect to the ketone body AcAc, which was increased by the KD and enhanced the binding of mutant BRAF (but not wild-type BRAF) to MEK1 to promote MEK-ERK signaling and tumor growth." (PMID 35851093, 2022). "The other reported negative prognostic factors were Kras mutation, BRAF mutation, intrahepatic recurrence, LTP at the 6-month follow-up, high tumor grade, distant metastasis at diagnosis of the primary tumor, and previous radiation therapy." (PMID 36097234, 2022). "As stated in Methods, all patients with available tumor tissue sample were screened for mutations in the entire series of additional candidate genes (KRAS, ALK, BRAF, MET) regardless of the positive or negative result of the EGFR mutation testing." (PMID 35012520, 2022). "Among those with tumor progression during 2L CPI therapy, 41 patients received subsequent tumor treatment with an overall number of 70 treatment lines, which comprised the re-introduction of BRAF ± MEKi (n = 39), CPI (n = 29) or chemotherapy (n = 2)." (PMID 35565212, 2022). "High T cell proximity score was strongly associated with proximal tumour location (P = 0.0003), low disease stage, absence of lymphovascular invasion, MMR deficiency and BRAF mutation (all P < 0.0001)." (PMID 35449453, 2022). "The BRAF V600E mutation, gender, multifocality, tumor location, and capsular invasion had no significance for LNM but bilateral tumors are associated with LNM in BRAF V600E-related PTCs." (PMID 35784548, 2022). "Targeted therapy consists of BRAF inhibitors (e.g., dabrafenib), MEK inhibitors (e.g., trametinib), combination of BRAF and MEK inhibitors, BCR-ABL tyrosine kinase inhibitors (e.g., imatinib), or tumor agnostic treatment (e.g., larotrectinib)." (PMID 35001359, 2022). "We report herein two cases of tubero-infundibular and ventricular Papillary Craniopharyngiomas in which BRAF/MEK inhibitor combined therapy was used as adjuvant (Case 1) or neoadjuvant (Case 2) treatment, with a 90% reduction in tumor volume observed after only 5 months." (PMID 35757402, 2022). "The upfront treatment with BRAF inhibitors resulting in substantial tumor regression has enabled non-mutilating complete surgical removal, ad integrum bone regeneration, and organ preservation." (PMID 36127985, 2022). "Thus, patients receiving a first-line therapy with a BRAF and MEK inhibitor combination achieved a rapid decrease in tumor burden and improvement in their symptoms." (PMID 35885042, 2022). "MAPK pathway evaluation revealed a marked decrease in the expression level of the phosphorylated form of key pathway-related enzymes, BRAF and ERK1/2 following treatments in comparison to the untreated group, supporting their involvement in tumor growth inhibition." (PMID 36168618, 2022). "We further demonstrated BRAF score's ability to differentiate between BRAF V600E mutants and wild‐type samples by comparing the BRAF scores between the two groups in two cell line datasets (GDSC and CCLE) and two external tumor datasets (GSE59455 and GSE81383)." (PMID 35044091, 2022). "In a study that adopted the MCF-7 cell xenograft model, it was reported that TAM and BD co-treatment could significantly enhance cell apoptosis, suppress tumor growth, and increase the expression of TAM resistance proteins BRAF and p21." (PMID 35721162, 2022).
tumor (continued). "This last one is a multikinase inhibitor that not only acts on angiogenic protein kinases (VEGFR-1, VEGFR-2, VEGFR-3, TIE-2), but as well on proteins involved in oncogenesis (KIT, RET, RAF-1, BRAF, BRAFV600), metastasis (PDGFR, FGFR), and tumor immunity (CSF1R)." (PMID 35356214, 2022). "Nonetheless, DEL-22379 demonstrated significant anti-tumor effects against BRAF-mutant cells in vivo with an apparent lack of toxicity, making it an interesting candidate for the development of combinatorial treatments." (PMID 36056964, 2022). "Such research must include translational objectives and patient biospecimens to deepen our understanding of the interaction between BRAF/MEKi, CPI, tumour characteristics and the immune microenvironment to direct patient selection or to unveil novel therapeutic strategies." (PMID 35366166, 2022). "This is consistent with the previously reported study concerning inhibition of tumor growth by Furin silencing in KRAS or BRAF mutated cells but not in wild-type KRAS and BRAF cells." (PMID 35267511, 2022). "BRAF, ATRX, IDH1, and CDKN2A showed significant SNV alterations in most tumour types." (PMID 36186436, 2022). "NGS analysis of her GIST lesion revealed a quadruple wild-type tumor (no mutations in c-KIT, PDGFRA, SDH, RAS-P [RAS, BRAF, NF-1]) with a FGFR3 p.G145S mutation/variant which is of a germline rather than somatic variation." (PMID 35885469, 2022). "Tumor-related factors associated with an increased risks of recurrence or mortality in smokers include a T3 tumor, one to three affected lymph nodes, nonmetastatic diseases, a mutated KRAS status, and a wild-type BRAF status." (PMID 35207186, 2022). "Preclinical data suggest that BRAF and MEK inhibitors result in immunomodulatory changes in the tumor microenvironment; early data in murine models further suggest that these changes could enhance sensitivity to ICIs." (PMID 36428582, 2022). "Tumor intrinsic features, such as KRAS, NRAS and BRAF mutational status, did not interact with the survival effect of 25(OH)D levels (p = 0.773) and this was in line with a recently published review." (PMID 35681576, 2022). "In this pathway, BRAF phosphorylates and activates MEK that in turn phosphorylates and activates ERK, a potent effector that induces the transcription of many important genes that play a dominant role in survival and development of tumor cells." (PMID 35494017, 2022). "Nevertheless, there was no alteration of visually estimated percentage tumor nuclei in the progressed tumors compared to the tumors prior to BRAF/MEK-inhibition." (PMID 35058553, 2022). "BRAF/MEK inhibitors drived NKX2-1 positive tumor cells into a stationary state, while NKX2-1 negative cells cannot exit the cell cycle after the same treatment." (PMID 36703749, 2022). "In particular, 16.7% of patients with 1L CPI therapy showed an ongoing response upon 1L CPI therapy, whereas only 7.9% of patients treated with 1L BRAF ± MEKi did not experience tumor progression at any time during the follow-up period." (PMID 35565212, 2022). "Significant regulation of 8 out of 14 phosphosites (termed ‘oncogene addiction phosphorylation signature’, OAPS) that are modulated by METi in MET-addicted systems was detected also in EGFR-, ALK- and BRAF-addicted cellular tumor models following EGFR, ALK and BRAF targeting, respectively." (PMID 36494469, 2022). "Alternatively, in the case of negative results due to a very low number of tumor cells, a liquid biopsy can now open up new promises to evaluate the BRAF status in these patients." (PMID 35328303, 2022). "The presence of PD-L1 in the primary tumor was linked to a reduced chance of survival, whereas RAS and BRAF status were not." (PMID 35885491, 2022). "Finally, in our opinion, definitive treatment should be provided early after a partial or near complete response to BRAF/MEK inhibitors and adapted to the anatomical location and volume of the tumor remnants as well as their surgical accessibility." (PMID 35757402, 2022).